FANCD2 (FA complementation group D2)
Diseases named in the same sentence as FANCD2 in open-access papers (continued):
Sharing a sentence is not in itself a finding about the gene and the disease.
hepatocellular carcinoma (15 papers, 2010 to 2025). A malignant tumor that arises from hepatocytes. "FANCD2 is up-regulated in hepatocellular carcinoma tissues, elevated FANCD2 expression is associated with poorer prognoses, larger tumor size, and invasive phenotypes, as well as knockdown of FANCD2 attenuates hepatocellular carcinoma cell proliferation and invasion." (PMID 36814203, 2023). "Its high expression was predictive of poor outcome of the disease, hence indicating FANCD2 as potential novel biomarker and immunotherapeutic target against Hepatitis B-related hepatocellular carcinoma." (PMID 38903178, 2024). "The heightened FANCD2 expression has been correlated with an enlarged tumor size, a highly aggressive tumor phenotype, and an unfavorable prognosis in cases of hepatocellular carcinoma." (PMID 38443946, 2024). "The SNHG1-miR-199a-FANCD2/G6PD axis inhibits ferroptosis in hepatocellular carcinoma, serving as a potential marker for prognosis and therapy." (PMID 39315094, 2024). "An elevated magnitude of FANCD2 expression, concomitant with the unfavorable prognostic outlook of patients, has been detected in cases of endometrial cancer, hepatocellular carcinoma and ovarian carcinomas." (PMID 38443946, 2024). "FANCD2, which regulates ferroptosis, was also found overexpressed in Hepatitis B-related hepatocellular carcinoma." (PMID 38903178, 2024). "At present, some previous evidence has demonstrated the function of FANCD2 in promoting tumor development, such as nasopharyngeal carcinoma, melanoma, and hepatocellular carcinoma." (PMID 36814203, 2023). "Studies have demonstrated that FANCD2 has a strong resistance to tumor suppression by regulating DNA repair activity in hepatocellular carcinoma cells in vitro." (PMID 37369808, 2023). "According to our analysis, there was no statistical difference in FANCD2 expression between males and females in hepatitis B-associated hepatocellular carcinoma." (PMID 37821996, 2023). "The hepatocellular carcinoma (HCC) line HuH-7 was defective in FANCD2 monoubiquitination and FANCD2 nuclear focus formation but proficient in RAD51 focus formation." (PMID 20509860, 2010). "However, the mechanism of action of FANCD2 in Hepatitis B-related hepatocellular carcinoma (HCC) remains unknown." (PMID 37821996, 2023).
lung adenocarcinoma (14 papers, 2016 to 2025). A carcinoma that arises from the lung and is characterized by the presence of malignant glandular epithelial cells. "FANCD2 can predict the survival, tumor immunity, chemotherapy sensitivity, and mutation burden of lung adenocarcinoma." (PMID 36814203, 2023). "To investigate if this effect is SCC specific, we compared the expression of FANCD2 upon treatment with AZ1 in a lung adenocarcinoma cell line, NCI-H1299, versus an SCC cell line, LUDLU-1." (PMID 34611298, 2022). "On the basis of its upregulation, FANCD2 may contribute to tumorigenesis and impart an unfavorable prognosis to various types of cancers, including esophageal squamous cell carcinoma, head and neck cancer, nasopharyngeal carcinoma, and lung adenocarcinoma." (PMID 39051418, 2024). "Clinical characteristics of lung adenocarcinoma (LUAD) and lung squamous carcinoma (LUSC) patients with FANCD2 high or low expression based on TCGA database." (PMID 35646059, 2022). "Fanconi anemia complementation group D2 (FANCD2) is involved in the regulation of tumorigenesis, apoptosis, and other life processes in cancers, such as glioblastoma, esophageal squamous cell carcinoma (ESCC), and lung adenocarcinoma." (PMID 36814203, 2023).
glioblastoma (12 papers, 2014 to 2026). The most malignant astrocytic tumor (WHO grade IV). "In addition, a high expression level of FANCD2 is associated with chemotherapeutic drug resistance in glioblastomas." (PMID 37821996, 2023). "Elevated FANCD2 expression is correlated with a poor prognosis in primary and recurrent glioblastoma, silencing of FANCD2 inhibits cell survival." (PMID 36814203, 2023). "In glioblastoma, the expression FANCD2 was confirmed to promote drug resistance through attenuating ferroptosis while the inhibition of FNACD2 increased the ROS level and suppress cell survival." (PMID 36578929, 2022). "To test this, we quantified the expression of the key FA pathway protein FANCD2 in 131 archived FFPE glioblastoma specimens collected at the Royal Hallamshire Hospital's neuro-oncology department." (PMID 25071006, 2014). "Furthermore, high expression of FANCD2 can promote temozolomide resistance in glioblastoma cells by attenuating ferroptosis, while FANCD2 knockdown increases the levels of ROS and inhibits cell survival." (PMID 36814203, 2023). "FANCD2 promotes temozolomide resistance by slowing ferroptosis in glioblastoma cells." (PMID 36814203, 2023). "At the molecular level, VPA leads to a downregulation of FANCD2 and RAD51, and the eradication of glioblastoma cells." (PMID 37763083, 2023).
bladder cancer (10 papers, 2013 to 2022). "FANCD2 is an intersection protein associated with multiple ferroptosis in clear cell renal cell carcinoma and bladder cancer." (PMID 36686830, 2022). "Together, this supports the idea that coffee and caffeic acid may increase the risk of bladder cancer, particularly in people with germline or sporadic mutations in the DNA repair protein FANCD2." (PMID 27399778, 2016). "In accordance with the reports describing ΔNp63 as an oncogene, up-regulation of ΔNp63 by the inactivated/de-ubiquitinated form of FANCD2 promotes bladder cancer proliferation and invasion." (PMID 34638302, 2021). "Inhibition of FOXM1 expression using siFOXM1 in both 5637 and KU7 bladder cancer cell lines significantly reduced FANCD2 expression at both the mRNA and protein levels." (PMID 32486251, 2020). "This indicates that the tumorigenicity of inactivated FANCD2 in human tumors, such as human bladder cancer, is at least partly attributed to the subsequent elevation of ΔNp63." (PMID 23965832, 2013). "Thus, the high expression of FANCD2 in bladder cancer samples allows tumour cells to be less sensitive to ferroptosis to further promote the proliferation and growth of cancer." (PMID 34095228, 2021). "We then assessed whether FOXM1 and FANCD2 affect the recurrence of bladder cancer by analyzing their expression in clinical tissues." (PMID 32486251, 2020). "However, our previous study of gene expression profile analysis identified FOXM1 and FANCD2 as recurrent biomarkers of bladder cancer." (PMID 32486251, 2020). "After we transfected bladder cancer cell lines with control scRNA or siFOXM1, MMC was used to treat cells, and FANCD2-foci were observed during the DNA repair process." (PMID 32486251, 2020). "The results showed that the formation of FANCD2-foci was significantly reduced by suppression of FOXM1 expression in 5637 and KU7 bladder cancer cell lines." (PMID 32486251, 2020). "Defects in the DNA repair protein Fanconi Anemia D2 (FANCD2) also play an important role in the development of a variety of cancers (e.g., bladder cancer) in people without this genetic disease." (PMID 27399778, 2016). "Importantly, the induction of ΔNp63 expression in bladder cancer is due to transcriptional regulation by de-ubiquitinated FANCD2 protein and not an indirect consequence of abrogated FA signaling." (PMID 34638302, 2021). "Moreover, we determined the protein levels of FOXM1 and FANCD2 by IHC (Immunohistochemistry) in 57 bladder cancer samples (30 nonrecurrent primary tumors and 27 recurrent primary tumors) using a tissue microarray." (PMID 32486251, 2020). "Thus, we infer that FADS2, FANCD2 and HMGCR play a negative role in ferroptosis during bladder cancer development." (PMID 34095228, 2021).
clear cell renal cell carcinoma (10 papers, 2021 to 2022). "Overexpression of FANCD2, as an ferroptosis-related suppressor gene, might be an important prognostic indicator in clear cell renal cell carcinoma." (PMID 35874632, 2022). "For example, FANCD2 expression correlated with the activation of apoptotic and EMT pathways in clear cell renal cell carcinoma." (PMID 36276091, 2022). "A study indicated that FANCD2 expression correlated with the activation of apoptotic, cell cycle, and EMT pathways in clear cell renal cell carcinoma." (PMID 34422642, 2021).
esophageal squamous cell carcinoma (10 papers, 2015 to 2024). Esophageal squamous cell carcinoma (ESCC) is a type of esophageal carcinoma (EC) that can affect any part of the esophagus, but is usually located in the upper or middle third. "One study suggested that POLQ inhibition and FANCD2 deficiency activate cGAS-STING in esophageal squamous cell carcinoma." (PMID 36976649, 2023). "Increased risk of esophageal squamous cell carcinoma (ESCC) was reported to be associated with mutations in FANCD2, FANCE, FANCL, and FANCA in patients from an Iranian population." (PMID 26596371, 2015). "Previous research has suggested that the amplification of FANCD2 in esophageal squamous cell carcinoma leads to the emergence of a malignant nature, thereby promoting the progression of the tumor." (PMID 38443946, 2024). "The POLQ and/or FANCD2 KO esophageal squamous cell carcinoma (ESCC) cells had a considerably higher number of micronuclei." (PMID 35741863, 2022). "FANCD2 overexpression increases the risk of metastasis in esophageal squamous cell carcinoma (ESCC) by activating DNA replication and regulating cell cycle progression, which is associated with the negative prognosis of ESCC." (PMID 36203872, 2022).
melanoma (10 papers, 2016 to 2023). A malignant, usually aggressive tumor composed of atypical, neoplastic melanocytes. "As for the other half of the FANCD2-FANCI dimer, FANCD2 was reported as upregulated in melanomas and colorectal carcinoma and was associated with aberrant cell cycle and proliferation." (PMID 37324186, 2023). "Alternatively, the effect of FANCA deficiency in melanoma cells could have a less severe effect in term of senescence and ROS production than FANCD2 depletion." (PMID 27827420, 2016). "FANCD2 is a key factor in maintaining melanoma cell proliferation and survival and is a promising target for the treatment of melanoma." (PMID 37821996, 2023). "A similar trend was seen in melanoma, within SLX4, POLE, BRCA1, FANCD2, and ERCC6-mutated tumors containing a significantly higher mutational burden than overall melanoma." (PMID 27004405, 2016). "As previously observed for human melanoma cell lines, 3 days after transfection both MiTF and Fancd2 siRNA reduced their corresponding protein expression level and MiTF siRNA in B16-F10 triggered a G0/G1 cell cycle arrest." (PMID 27827420, 2016). "In concordance, inhibition of histone deacetylases class I resulted in suppression of HR due to down-regulation of RAD51 and FANCD2 and sensitized malignant melanoma cells to a synthetic lethal effect of olaparib combined with alkylating drug temozolomide." (PMID 27705909, 2016). "It is noteworthy that silencing of FANCD2 in melanoma cells recapitulates all the key cellular phenotypes of FA cells while FANCA depletion fails to induce a significant increase in the intracellular level of ROS." (PMID 27827420, 2016). "Melanoma cells have a higher FANCD2 expression, FANCD2 promotes the proliferation and survival of melanoma cells, and may serve as a biomarker for melanoma." (PMID 36814203, 2023). "In melanoma, the knockdown of FANCD2 suppressed the migration and proliferation of the tumor cells." (PMID 37324186, 2023). "The overexpression of FANCD2 was involved in metastasis-prone melanomas and colorectal cancer." (PMID 35236309, 2022). "Immunohistochemical results suggested SLC7A11 and FANCD2 staining in melanoma." (PMID 35309947, 2022). "Notably, several consequences of MiTF depletion in melanoma were recapitulated by FANCA or FANCD2 depletion despite the maintenance of MiTF expression; inversely, their overexpression limits the consequence of MiTF depletion on melanoma cell behaviour." (PMID 33723374, 2021). "Moreover, FANCA or FANCD2 knockdown dramatically reduced the migration ability of the melanoma cells and suppressed their capacity to sustain anchorage-independent cell growth, which are indicators of tumorigenicity and invasiveness." (PMID 27827420, 2016). "The forced expression of FANCA or FANCD2 in MiTF-depleted cells significantly reduced the occurrence of spontaneous DNA damage, as indicated by γH2AX and 53BP1 foci formation and foster melanoma cell proliferation in response to MMC exposure." (PMID 27827420, 2016). "We wondered if FANCD2 could influence vemurafenib response in BRAFV600E melanoma cells." (PMID 27827420, 2016). "To validate that increased DNA damage and cellular senescence in MiTF-silenced melanoma cells relied directly on the downregulation of the FANC pathway, we carried out experiments involving the forced expression of FANCA or FANCD2." (PMID 27827420, 2016). "Specifically, less than 10% of exponentially growing melanoma cells displayed more than five 53BP1 foci per nucleus, a percentage that exceeded 60% when MiTF, FANCA or FANCD2 were silenced individually." (PMID 27827420, 2016). "Consequently, since the FANC pathway appears to oppose the efficiency of targeted therapies, specific inhibitors of FANCD2 activity/activation or inducers of its degradation could be useful therapeutic agents for increasing the efficiency of current melanoma treatments." (PMID 27827420, 2016).
melanoma (continued). "In line with a crosstalk between MiTF and the FANC pathway, MiTF silencing in melanoma cells triggered a strong reduction in the mRNA level of 4 analysed FANC genes: FANCA, FANCD2, FANCC and FANCG." (PMID 27827420, 2016). "Altogether, our results demonstrate that FANCD2 participates in the cellular resistance of melanoma cells even to non-DNA damage therapeutics." (PMID 27827420, 2016). "Although not really specific for FANCD2, their utilization as therapeutic agents could open new opportunities to increase the efficiency of melanomas treatments." (PMID 27827420, 2016). "Moreover, MiTF-depleted cells presented a cellular and chromosomal hypersensitivity to ICL-inducing agents similar to that reported in FANCA- or FANCD2-depleted melanoma cells (e and data not shown)." (PMID 27827420, 2016).
osteosarcoma (10 papers, 2014 to 2025). A usually aggressive malignant bone-forming mesenchymal neoplasm, predominantly affecting adolescents and young adults. "Meanwhile, FANCD2 knockdown predisposed osteosarcoma cells to ferroptosis by regulating the JAK2/STAT3 pathway." (PMID 36814203, 2023). "To obtain novel insights into FANCD2 function independent of the DNA damage response, we performed mass spectrometry using the human osteosarcoma U2OS cell line stably expressing FLAG epitope-tagged FANCD2 (FLAG–FANCD2)." (PMID 41065314, 2025). "In this research, we detected the role of FANCD2 on ferroptosis of osteosarcoma cells, FANCD2 knockdown reduced the levels of FTH1 and GPX4, and elevated COX2, increased the levels of iron, LIP, Fe2+, and promoted lipid peroxidation." (PMID 36814203, 2023). "In the present study, we investigated the function of FANCD2 silencing on osteosarcoma cells, tumor growth, and ferroptosis." (PMID 36814203, 2023). "This research aimed to investigate the roles of fanconi anemia complementation group D2 (FANCD2) on the regulation of ferroptosis in osteosarcoma progression." (PMID 36814203, 2023). "Similar to previous research, in the present study, FANCD2 expression was obviously up-regulated in osteosarcoma cells." (PMID 36814203, 2023). "In the present study, colivelin reduced the inhibitory effects of FANCD2 up-regulation and also erastin (a ferroptosis inducer) on cell viability, invasion, migration, and inhibited ferroptosis of osteosarcoma cells." (PMID 36814203, 2023). "In our study, these results indicated that FANCD2 silencing inhibited osteosarcoma cells and tumor growth, as well as promoted ferroptosis by activating JAK2/STAT3 pathway." (PMID 36814203, 2023). "Taken together, we indicated that FANCD2 may mediate ferroptosis in osteosarcoma by JAK2/STAT3 pathway to regulate tumor cell growth." (PMID 36814203, 2023). "Taken together, we suggested that FANCD2 knockout contributed to promoted ferroptosis of osteosarcoma cells, thereby inhibiting the progression of osteosarcoma, targeting ferroptosis through FANCD2 may be a potential strategy." (PMID 36814203, 2023). "In addition, knockdown of FANCD2 decreased cell viability and proliferation, inhibited the ability of invasion and migration of osteosarcoma cells, and suppressed tumor growth in xenograft models." (PMID 36814203, 2023). "FANCD2 knockdown reduced cell viability, invasion, and migration of osteosarcoma cells." (PMID 36814203, 2023). "Taken together, FANCD2 silencing inhibited the malignant phenotype of osteosarcoma." (PMID 36814203, 2023). "Secondly, whether FANCD2 can be used as a prognosis marker for osteosarcoma needs to be demonstrated in clinical samples." (PMID 36814203, 2023). "The levels of FANCD2 were detected in osteosarcoma cells (MG-63 and U2OS cells)." (PMID 36814203, 2023). "Our results may FANCD2 may provide a novel marker for osteosarcoma and a potential therapeutic strategy for clinical treatment." (PMID 36814203, 2023). "In summary, in this research, we investigated the function of FANCD2 on osteosarcoma cells." (PMID 36814203, 2023). "Based on previous research, we speculated that FANCD2 interacts with JAK2/STAT3 pathway to mediate osteosarcoma development." (PMID 36814203, 2023). "Based on previous studies, we speculated that FANCD2 may regulate osteosarcoma progression by mediating ferroptosis." (PMID 36814203, 2023). "However, it is unclear on the relationship between JAK2/STAT3 pathway and FANCD2 in osteosarcoma." (PMID 36814203, 2023). "Finally, more deep action mechanisms of FANCD2 in osteosarcoma still need to be further studied." (PMID 36814203, 2023). "However, the role of FANCD2 in regulating ferroptosis of osteosarcoma cells remains unclear." (PMID 36814203, 2023).
osteosarcoma (continued). "In addition, JAK2 and STAT3 expression were reduced by silencing of FANCD2, and STAT3 activator (colivelin) distinctly reversed tumor suppressor effects of FANCD2 silencing on osteosarcoma development." (PMID 36814203, 2023). "However, the detailed roles of FANCD2 in osteosarcoma development are not fully clear." (PMID 36814203, 2023).